IL17F (interleukin 17F)
Diseases named in the same sentence as IL17F in open-access papers (continued):
Sharing a sentence is not in itself a finding about the gene and the disease.
asthma (continued). "In addition, it has been demonstrated that Th17 cells and their cytokines such as IL-17A and IL-17F are involved in the pathogenesis of severe asthma." (PMID 23577040, 2013). "The top pathways enriched for these genes included TNFR2 Signalling, Interferon Signalling, Differential Regulation of Cytokine Production in Intestinal Epithelial Cells by IL-17A and IL-17F, Airway Inflammation in Asthma, Glucocorticoid Receptor Signalling and T Helper Cell Differentiation." (PMID 22701743, 2012). "IL-17F is potentially involved in the pathogenesis of asthma." (PMID 22013453, 2011). "Taken together, the IL-17F/CCL20 axis may have an orchestrating role in the pathogenesis of asthma and could possibly provide a valuable therapeutic target for development of new strategies to treat asthma." (PMID 22013453, 2011). "Moreover, a recent study showed that IL-17F has a possible role in the mechanism of steroid resistance in asthma." (PMID 22013453, 2011). "However, further in vivo study is needed to clarify the importance of the IL-17F/CCL20 axis in asthma." (PMID 22013453, 2011). "Th17 cells selectively produce hallmark cytokines IL-17A and IL-17F, but not IL-4 and INFγ, and they play a pivotal role in airway diseases including asthma." (PMID 22013453, 2011). "In asthma, IL-17F may play an important regulatory role and seems to function differently than IL-17A." (PMID 21858022, 2011). "IL17F was investigated as an asthma candidate gene because of its function i.e. IL17F is one of the cytokines produced by activated mast cells, CD4+ T cells, and basophils and can upregulate IL6 and IL8 transcripts and protein expression in primary bronchial epithelial cells." (PMID 18197984, 2008). "Th17 produces IL-17A and IL-17F, which are elevated in some individuals with asthma and may be responsible for the recruitment of antigen-induced neutrophils into the airways and the enhancement of Th2 cell-mediated eosinophil recruitment into the airways, as seen in steroid-resistant asthma." (PMID 39598135, 2024). "Other studies have found that IL-17F, but not IL-17A, underlies airway inflammation in steroid-insensitive toluene diisocyanate-induced asthma models and that anti-IL-17F ameliorates toluene diisocyanate-induced AHR and airway neutrophilia with a reduced Th17 response." (PMID 37377958, 2023). "The TH17 lymphocytes producing IL-17A and IL17-F cytokines, may have a role on asthma inflammation." (PMID 31168303, 2019). "Hence, IL-17F may play an orchestrating role in the pathogenesis of asthma and may provide a valuable therapeutic target for development of novel strategies." (PMID 24829928, 2014). "The suppression of all the symptoms of asthma in the present study was associated with reduced levels of various Th1 cytokines (TNF-α, IL-6, and IL-1β), with reduced levels of various Th2 cytokines (IL-4, IL-5 and IL13) and with reduced levels of a Th17 cytokines (IL-17F) in splenocytes." (PMID 23346203, 2012). "The IL-17F/CCL20 axis may be a novel pharmacological target for asthma." (PMID 22013453, 2011). "These cell types may play crucial roles in asthma in response to IL-17F." (PMID 22013453, 2011). "IL-17A and IL-17F are both involved in the pathogenesis of neutrophilic inflammation observed in COPD and severe asthma." (PMID 34075087, 2021). "Intratracheal administration of S. commune in OVA-induced asthma model mice enhanced neutrophilic airway inflammation, increased the mRNA expression of CXCL1 and CXCL2 in the lungs, and provoked IL-17A, and IL-17F production in BAL fluid." (PMID 31852931, 2019). "The pathogenesis of TDI-induced asthma in at least one mouse model depends on the Th17 response: IL-17A suppresses TH2 inflammation with eosinophil recruitment, whereas IL17F drives Th17 inflammation and neutrophil increase in airways." (PMID 31816917, 2019). "IL-17F is derived from activated CD4+ T cells, basophils, and mast cells, three key-effector cell types involved in asthma." (PMID 22013453, 2011).
asthma (continued). "There are biomarkers useful for various phenotypes of non-eosinophilic and T2 low asthma; Th17 cells may be responsible for associated with a severe asthma phenotype, which is characterized by neutrophilic inflammation and interleukins such as IL-17A, IL-17F, IL-21 and IL-22." (PMID 40980110, 2023). "This mouse model typically reflects eosinophilic mild-to-moderate T2 asthma and does not display a significant increased release of IL-17A or IL-17F." (PMID 35883573, 2022). "It was found that IL-17A, IL-17F and IL-22 were increased in peripheral blood mononuclear cells (PBMCs), bronchoalveolar lavage fluid (BALF) and sputum of asthmatic patients, mainly in those with severe asthma." (PMID 33013382, 2020). "Studies have demonstrated the important role of IL-17 pathway in pulmonary diseases, specially in asthma, considering that the overexpression was demonstrated of IL-17A and IL17F in lungs of non-atopic asthmatic patients." (PMID 31168303, 2019). "Th17 cells produce some pro-inflammatory cytokines, particularly IL-17A, IL-17F, IL-21, IL-22, TNF-α, and GM-CSF, which may have important roles in the reinforcement of severe form of asthma." (PMID 30116273, 2018). "As IL-17A and IL-17F cell frequency was very low in the OVA-asthma mice (data not shown), we were not able to detect alteration of Th17 cell frequency after cell therapy." (PMID 22792275, 2012). "IL-17F plays a crucial role in airway inflammatory diseases including asthma, but its function has not been fully elucidated." (PMID 22013453, 2011). "IL-17F: This cytokine, closely related to IL-17A, engages the same receptors and exhibits comparable pro-inflammatory effects, although its specific role in asthma is not yet fully elucidated." (PMID 40564060, 2025). "We found that S. commune, a ubiquitous basidiomycetous fungus in the environment, induces neutrophilic airway inflammation in non-fungus-induced asthma model mice and that IL-17A and IL-17F have central roles in the neutrophilic airway inflammation induced by S. commune." (PMID 31852931, 2019). "Another putative mediator of severe asthma, IL-17F, has been shown to induce IGF-1 expression in bronchial epithelial cells along or by costimulation with IL-4 and IL-13, suggesting an important relationship among IGF-1 signaling, Th2, and Th17 cells in asthma." (PMID 30018981, 2018). "This study shows that mRNA IL-17F levels and soluble IL-17F was higher in patients with asthma compared with the control group, although it has not been able to mention relationship with the severity of asthma." (PMID 28606156, 2017). "Brodalumab, a humanized mAb that binds to IL-17RA, thereby blocking the receptor and the downstream signal pathways of IL-17A, IL-17F, and other IL-17 isoforms, also did not achieve improvement in patients who were taking ICS and had inadequately controlled moderate-to-severe asthma." (PMID 39194521, 2024). "However, while the 3 mg protein/ml SHE solution did not induce asthma, co-exposure with DEP resulted in a markedly enhanced AHR (p = 0.002) and eosinophilic inflammation (p = 0.004), with increased levels of IL-5, IL-17F and CCL20 and decreased levels of IFN-γ." (PMID 28628664, 2017).
colitis (77 papers, 2010 to 2025). Inflammation of the colon. "IL-17F deficiency resulted in reduced pathology of DSS-induced colitis in mice, whereas IL-17A deficiency was associated with more severe disease." (PMID 39354587, 2024). "IL-17A and IL-17F have contrasting roles in colitis models, with IL-17A suppression causing excessive inflammation and IL-17F having protective roles." (PMID 39364475, 2024). "Adoptive transfer of T cells deficient in Th17-associated cytokines (IL-17A, IL-17F, and IL-22) into Rag1 knockout mice induced severe colitis comparable to that induced by wild-type cells." (PMID 37239894, 2023). "A population of CD4+IL-17F+ T cells was sufficient to induce colitis in RAG1-deficient recipients, where the transition of these precursors to Th1-like cells was an absolute requirement for disease." (PMID 36012618, 2022). "Previous studies have reported that colitis is associated with an increase in IL-17A subunit levels, while IL-17F subunit expression is inversely correlated with gut inflammation, which subsequently prompts neutrophil recruitment into the ileum." (PMID 35466218, 2022). "Studies in the dextran-sulfate sodium (DSS)-induced colitis model revealed that IL17F deficiency leads to colitis reduction, whereas IL17A deficiency resulted in a more severe course of the disease." (PMID 33859636, 2021). "In mouse models, the constitutive expression of IL-17RC in intestinal epithelial cells explains the more pathogenic effects of IL-17F than IL-17A on microbiota during colitis." (PMID 33244315, 2020). "A few studies have demonstrated that the blocking of Th17 derived IL-17A increased the dextran sodium sulfate (DSS)-colitis symptoms (a protective meaning), and IL-17F deficiency relieved the symptoms of colitis (a proinflammatory meaning)." (PMID 32630805, 2020). "As consequence, chemically-induced colitis was milder in mice deficient of IL-17F than that of IL-17A-deficient or wild type mice." (PMID 33244315, 2020). "IL-17F-deficiency improves the development of DSS-induced murine colitis, whereas IL-17-deficiency exaggerates the development of DSS-induced murine colitis, indicating that IL-17F rather than IL-17A is important in sustaining DSS colitis." (PMID 31886308, 2019). "In a colitis model caused by dextran sulfate sodium, IL-17A deficiency enhanced colitis, whereas IL-17F deficiency reduced colitis." (PMID 31447673, 2019). "This idea is supported by the demonstration that mice deficient in IL-17F are largely resistant against DSS-colitis." (PMID 22082127, 2011). "IL-21-deficient mice are largely protected against DSS- and TNBS-colitis, and this protection is associated with a marked decrease in IL-17A and IL-17F, thus confirming the key role of IL-21 in sustaining Th17 immunity." (PMID 22082127, 2011). "We also assessed the expression of genes encoding colitis-associated cytokines that influence susceptibility to C. rodentium infection, including IL-17A and IL17F, IL-22, and IL-23." (PMID 20485566, 2010). "Using a mouse model of HFD + trinitrobenzene sulfonic acid (TNBS)-induced colitis, dietary n-3 PUFAs have been shown to reduce colitis-associated disease severity and colonic mRNA expression of cytokines (IL-6, IL-17A, IL-17F, IL-21, IL-23, and IFNγ) versus corn oil in control HFD mice." (PMID 40219010, 2025). "Furthermore, IL-17F has been shown to play a protective role in mouse CAC induction, which is associated with the important role of IL-17F in maintaining the barrier integrity in epithelial cells in the murine colitis model." (PMID 39906741, 2024). "However, IL-17F plays the opposite role from IL-17A and protects mice from colitis-associated colorectal cancer (CAC) induction." (PMID 39906741, 2024). "Paradoxically, although one study had demonstrated that IL-17A-deficiency in prototypical Th1-type C57BL/6 mice reduced DSS colitis, a separate study using IL-17A- and IL-17F-deficient mice demonstrated a deleterious role for IL-17F in the development of disease." (PMID 36012618, 2022).
colitis (continued). "Taking the DSS-induced colitis mice models, for example, IL-17 knockout mice exhibited more severe colitis, whereas IL-17F deficiency mice showed moderated colitis, which suggests completely adverse functions between Il-17A and IL-17F." (PMID 28831399, 2017). "Although IL-17F has largely been ascribed pro-inflammatory roles and may play pathogenic roles in colitis models, it can also synergize with IL-22 to enhance production of anti-microbial peptides." (PMID 29085366, 2017). "In addition, the HF-FO diet reduced both colitis-associated disease severity and colonic mRNA expression of the Th17 cell master transcription factor (RORγτ) and critical cytokines (IL-6, IL-17A, IL-17F, IL-21, IL-23 and IFNγ) versus HF (P<0.05)." (PMID 23166761, 2012). "iTcES treatment resulted in a significant reduction in TNF-α, IL-1β, IL-23, IL-17F, and IL-33 levels; all of these cytokines are known to exacerbate colitis by promoting intestinal epithelial cell death and disrupting the epithelial barrier." (PMID 40576745, 2025). "In DSS colitis, Arg-1 deletion in myeloid cells attenuated the protective role of MDSCs during colitis by upregulating IL-17A and IL-17F, while the adoptive transfer of suppressive MDSCs alleviated colitis in ArgmyeKO mice." (PMID 40244120, 2025). "Elevated Th17 cells are associated with the pathogenesis of inflammatory bowel disease (IBD) and colitis through expressing rorγt, IL-17A, IL-17F, and IL-21 in the inflamed mucosa." (PMID 37344888, 2023). "In support, our findings demonstrated that blocking of both IL-17A and IL-17F had the most prominent effect on alleviation of colitis development, even though interfering either one also showed beneficial outcome." (PMID 36792629, 2023). "Although IL-17A and IL-17F are the important inflammatory cytokines, their function in colitis development is still debatable." (PMID 36792629, 2023). "TCRβ-/- mice transferred with CD4-Cu2++DSF T cells had lower IL-17A and IL-17F mRNA levels in DSS-induced colitis than those transferred with CD4 control." (PMID 37284442, 2023). "Nsun2 deficiency in Th17 cells impairs the stability of m5C-modified mRNAs, such as Il17a and Il17f, resulting in ameliorated colitis progression induced by Th17 cells." (PMID 36792629, 2023). "It is demonstrated that in colitis pathology, both IL-17A and IL-17F are involved in developing intestinal inflammation because these cytokines have overlapping or interdependent pro-inflammatory role." (PMID 37344888, 2023). "Collectively, these findings demonstrate that both IL-17A and IL-17F serve as the downstream targets of Nsun2 in Th17 cells and participate in the progression of colitis." (PMID 36792629, 2023). "Mice with a myeloid-specific deletion of TSC1 gene (TSC1cKO) displayed severe dextran sodium sulfate (DSS)-induced colitis accompanied by high levels of IL-17A, IL-17F, and IFN-γ." (PMID 36465179, 2022). "IL-17A and IL-17F have been established as the central pro-inflammatory cytokines in colitis, though a controversy regarding IL-17A is noted." (PMID 33871822, 2021). "A study in experimental colitis provided evidence that inhibition of both IL-17A and IL-17F was necessary to attenuate colitis." (PMID 34267743, 2021). "IL-17A can exist as a homodimer, or it can pair with IL-17F to form a heterodimer, both of which are present in the colon of hapten-induced colitis mice." (PMID 33553436, 2021). "In particular, Th1 (producing IFN-γ), Th17 (producing IL-17A and IL-17F) and Treg (producing IL-10) have been reported to be associated with Crohn’s Disease in humans and DSS-induced colitis in mice." (PMID 34407839, 2021). "In conclusion, we have demonstrated distinct roles of IL-17A and IL-17F in DSS-induced colitis mice model which was dependent on increased Arg-1 secreted by MDSC after ESR/STAT3 activation." (PMID 32391010, 2020).
colitis (continued). "We have shown a decreased expression of IL-17A in the colorectum during colitis, while a significantly up-regulated IL-17F level adversely aggravated epithelial injury and hastened ArgmyeKO mice death eventually." (PMID 32391010, 2020). "In contrast, IL-17F knockout mice are reported to be protected against chemically induced colitis, whereas IL-17A knockout mice remain sensitive." (PMID 31937680, 2020). "Together, these results suggested that Arg-1 deletion attenuates a protective role of MDSC during colitis by dichotomously regulating IL-17A and IL-17F levels in the colorectum, thus contributed to the exacerbation of colitis." (PMID 32391010, 2020). "The results showed that IL-17A mRNA expression was reduced, whereas that of IL-17F was abnormally increased in the colorectums of ArgmyeKO mice, indicating an opposite functions of IL-17A and IL-17F during colitis." (PMID 32391010, 2020). "Protection against C. rodentium is known to require IL-17a and IL-17f, however, IL-17f-deficient mice are resistant to dextran sodium sulfate (DSS)-induced colitis, presenting milder acute intestinal inflammation." (PMID 32082288, 2020). "High level of Arg-1 favors accumulation of IL-17A, but reduced IL-17F expression in the colorectum of mice and ultimately leading to relief of colitis, indicating a potential clinical impact of MDSC-derived Arg-1 for controlling inflammatory bowel disease." (PMID 32391010, 2020). "Given the opposite roles of IL-17A and IL-17F in colitis, we next evaluated genes regulated by IL-17 A/F." (PMID 32391010, 2020). "The discovery of distinct functions of IL-17A and IL-17F produced by TH17 cells highlights a central role for this cell population in regulating adaptive immunity during colitis." (PMID 32391010, 2020). "Although both IL-17A and IL-17F are produced by TH17 cells, we found lower expression of IL-17A, and significantly increased expression of IL-17F in ArgmyeKO mice during colitis." (PMID 32391010, 2020). "High level of Arg-1 facilitates TH17 cell polarization and enhances IL-17A expression but inhibits IL-17F level in the colorectum during colitis." (PMID 32391010, 2020). "Collectively, MDSC-derived Arg-1 promotes IL-17A expression in the colorectum, inhibits IL-17F expression and greatly relives colitis in mice." (PMID 32391010, 2020). "IL‐17f, an IL‐17a heterodimer partner, is a prime mediator of colitis, and we showed a significant reduction in this cytokine expression levels in FKK6‐treated mice compared to vehicle‐treated mice." (PMID 32153125, 2020). "In mice IL-17A expression has been proposed to benefit intestinal barrier function and IL-17F to weaken intestinal integrity, since IL-17A inhibition exacerbates induced colitis and IL-17F suppression is protective." (PMID 32010094, 2019). "IL-17A knockout (KO) mice were protected against 2,4,6-Trinitrobenzenesulfonic acid solution (TNBS)-induced colitis, and similarly, IL-17F KO mice had less severe DSS-colitis; however, interestingly, IL-17A KO mice had worse DSS-induced inflammation." (PMID 30103486, 2018). "Recently, however, in vivo studies of an induced model of colitis have shown that IL-17A and IL-17F can have differing roles." (PMID 29311948, 2017). "Real time RT-PCR quantitation confirmed that pro-inflammatory cytokines and chemokines (CCL2, IL-1β, IL-6, IL-23, TNF-α, IL-17A and IL-17F) were elevated in quiescent and active colitis biopsies." (PMID 27271344, 2016). "Whereas murine DSS-induced colitis was worsened in IL-17A KO mice, a clear improvement of the colonic inflammatory process was observed in IL-17F KO mice." (PMID 25101191, 2014). "In this regard, Yang and colleagues showed that murine DSS-induced colitis was worsened in IL-17A knockout (KO) mice but significantly improved in IL-17F KO mice." (PMID 22506136, 2012).